PMS2 (PMS1 homolog 2, mismatch repair system component)
Diseases named in the same sentence as PMS2 in open-access papers (continued):
Sharing a sentence is not in itself a finding about the gene and the disease.
leukemia (3 papers, 2012 to 2021). A malignant (clonal) hematologic disorder, involving hematopoietic stem cells and characterized by the presence of primitive or atypical myeloid or lymphoid cells in the bone marrow and the blood. "We also found mutations in genes with no reported association to the diagnosis of the patient, such as BRCA1 and PTCH1 mutations in neuroblastoma, as well as PMS2 mutations in leukemia." (PMID 33674644, 2021). "PMS2 recessive mutations have been associated with leukaemias." (PMID 22745689, 2012).
lymph node metastasis (3 papers, 2019 to 2024). "The expression of PMS2 had correlation with lymph node metastasis, gross appearance, and tumor location." (PMID 38967814, 2024).
metastatic tumor (3 papers, 2019 to 2024). "Conversely, MLH1, PMS2, CEA and EGFR expression was markedly more common in, and in same cases exclusive to, liver metastatic tumors." (PMID 32170146, 2020). "All cases showing loss of MLH1 (20% of cases) and PMS2 (25%) expression, and absence of CEA expression (22% of cases) were non-metastatic tumors; most liver metastatic tumors had a positive value of EGFR membranous expression (79% vs. 38% of non-metastatic cases)." (PMID 32170146, 2020).
mucinous adenocarcinoma (3 papers, 2014 to 2025). An invasive adenocarcinoma composed of malignant glandular cells which contain intracytoplasmic mucin. "Different, through homogenous, MMR protein expression patterns in distinct tumor compartments were observed in a mucinous adenocarcinoma (case 9) with loss of MLH1/PMS2 expression, MSI and MLH1 methylation in 1/7 tumor blocks that corresponded to an adenomatous tumor component." (PMID 24968821, 2014). "Additionally, PMS2-negative status was more frequently observed in signet-ring cell adenocarcinomas (20%) and mucinous adenocarcinomas (16.1%) compared to NOS adenocarcinomas (12.5%) or neuroendocrine tumors (0%), though these differences were not statistically significant (p = 0.531)." (PMID 40941629, 2025).
myotonic dystrophy type 1 (3 papers, 2013 to 2025). Steinert disease, also known as myotonic dystrophy type 1, is a muscle disease characterized by myotonia and by multiorgan damage that combines various degrees of muscle weakness, arrhythmia and/or cardiac conduction disorders, cataract, endocrine damage, sleep disorders and baldness. "A role for MLH3 had also been suggested from findings in a mouse model of myotonic dystrophy type 1 in which knockout of Pms2, encoding MLH1's major binding partner, reduced the rate of somatic CTG expansion by ∼50%, but did not eliminate somatic expansions." (PMID 24204323, 2013). "In the case of a mouse model of Myotonic Dystrophy type 1 (DM1), loss of PMS2 resulted in a ~50% decrease in the extent of somatic expansions." (PMID 32589669, 2020). "Furthermore, in a mouse model of Myotonic Dystrophy Type 1 (DM1), a CTG-repeat expansion disorder, loss of PMS2 results in the loss of ~50% of expansions in many organs." (PMID 39185211, 2025).
oligodendroglioma (3 papers, 2020 to 2023). A well-differentiated (WHO grade II), diffusely infiltrating neuroglial tumor, typically located in the cerebral hemispheres. "We observe that different genes belonging to this pathway exhibit different trends, for example genes such as POLD1(chr19), RPA2(chr1), and LIG1(chr19) loose a copy in IDH-mut oligodendrogliomas, while genes RPA3(chr19), PMS2(chr19), PCNA(chr20) and POLD2(chr7) gain a copy in IDH-wt GBM." (PMID 36918656, 2023).
ovarian endometrioid carcinoma (3 papers, 2021 to 2023).
ovarian tumors (3 papers, 2018 to 2025). "Another MLH1-methylated case was identified in a patient with an ovarian tumor at age 56 and CRC with loss of MLH1/PMS2 expression at age 60 (ID 1043), and she had a family history of LS-related tumors." (PMID 36077770, 2022).
prostate tumor (3 papers, 2015 to 2025). "Next-generation sequencing (NGS) of the original prostate tumor biopsy identified the presence of a somatic BRCA2 mutation, the patient’s germline PMS2 mutation, and 13.1 mutations/Mb tumor mutational burden (TMB)." (PMID 38879699, 2024). "Other studies also showed reduced PMS2 protein expression in prostate tumor regions as compared to normal adjacent." (PMID 26036629, 2015). "This pattern of PMS2 expression was also observed in the normal adjacent region of prostate tumor tissue." (PMID 26036629, 2015).
sebaceous neoplasm (3 papers, 2023 to 2025). "With a sample size of 28 cases, this study is the largest to perform systematic investigation of germline and somatic mechanisms of MLH1/PMS2-deficient sebaceous neoplasms." (PMID 40208414, 2025). "This study investigated germline and somatic mechanisms underlying MLH1/PMS2-deficiency in sebaceous neoplasms." (PMID 40208414, 2025). "This study demonstrates the importance of both germline and tumour testing in individuals diagnosed with MLH1/PMS2-deficient sebaceous neoplasms." (PMID 40208414, 2025). "Based on our findings, a potential testing strategy for people with MLH1/PMS2-deficient sebaceous neoplasms would be initial germline MMR gene testing to identify a MLH1 pathogenic variant coupled with MLH1 epimutation testing." (PMID 40208414, 2025). "However, findings from the sebaceous tumours we could test suggest biallelic somatic MLH1 mutations are a more likely cause of MLH1/PMS2-deficiency than somatic MLH1 hypermethylation." (PMID 40208414, 2025).
serous ovarian carcinoma (3 papers, 2018 to 2023). "Increased MSH6 and PMS2 mRNA expression was correlated with a favorable overall survival in serous ovarian cancer patients." (PMID 29063235, 2018). "Interestingly, our date showed that increased MSH6 and PMS2 mRNA levels were correlated with a favorable OS in serous ovarian cancer, but not in endometrioid ovarian cancer." (PMID 29063235, 2018).
stomach adenocarcinoma (3 papers, 2022 to 2024). "Pathological studies showed a poorly differentiated gastric adenocarcinoma with a loss of nuclear expression of MLH1 and PMS2, a combined positive score (CPS) of 100, and immunochemistry for HER2 negative." (PMID 39081436, 2024).
urothelial carcinoma (3 papers, 2021 to 2022). A malignant neoplasm derived from the transitional epithelium of the urinary tract (urinary bladder, ureter, urethra, or renal pelvis).
-deficiency (2 papers, 2018 to 2022). "Two of the four novel patients with PMS2-deficiency (P5 and P12) had truncating mutations affecting both PMS2 alleles and the other two (P9 and P16) were homozygous for splice mutations leading to aberrant out-of-frame transcripts." (PMID 30013564, 2018). "Furthermore, the number of patients is too little to confirm this observed trend of age-dependence or to suspect a genotype–phenotype correlation, especially since older patients in our study cohort included more individuals with PMS2 deficiency than individuals with other MMR deficiencies." (PMID 30013564, 2018). "Approximately 3% of ECs are caused by germline mutations in the MMR genes such as MLH1/2, MSH6, and PMS2 and are termed MMR-deficient (MMR-D) tumors." (PMID 35965548, 2022).
acute myeloid leukemia (2 papers, 2022 to 2023). Acute myeloid leukemia (AML) is a group of neoplasms arising from precursor cells committed to the myeloid cell-line differentiation.
bladder urothelial carcinomas (2 papers, 2021 to 2022). "The low frequency of PMS2 loss was also confirmed in the cohort of bladder urothelial carcinomas of The Cancer Genome Atlas (TCGA), as deletion occurred in just 2/408 cases." (PMID 36612181, 2022).
Breast tumor (2 papers, 2024 to 2025). "In this case, both endometrial and breast tumors demonstrated loss of MLH1/PMS2 expression, MSI-H, and prominent lymphocytic infiltration in poorly differentiated regions—histological features consistent with Lynch-related tumors." (PMID 41278281, 2025).
common variable immunodeficiency (2 papers, 2009 to 2018). "Increased microhomology at the CSR junctions has also been observed in mice deficient in PMS2, MLH1, MSH4 or MSH5 and in IgAD and common variable immunodeficiency (CVID) patients carrying mutations in the MSH5 gene." (PMID 19008195, 2009).
Crohn disease (2 papers, 2020 to 2023). A gastrointestinal disorder characterized by chronic inflammation involving all layers of the intestinal wall, noncaseating granulomas affecting the intestinal wall and regional lymph nodes, and transmural fibrosis.
duodenal carcinoma (2 papers, 2021 to 2023). "The second patient had duodenal carcinoma with pancreatic invasion, in which BRAF V600E was found to be a driver gene mutation in the WES and was immunohistochemically confirmed to have MLH1 and PMS2 deletions." (PMID 36999887, 2023).
endometrial endometrioid carcinoma (2 papers, 2021 to 2025). "Interestingly, OCCC synchronous with grade I-II endometrial endometrioid carcinoma, which is probably sporadic but does not completely exclude LS, was noted in 2 of 3 MLH1/PMS2-deficient patients." (PMID 33541386, 2021).
infiltrating ductal carcinomas (2 papers, 2016 to 2019).
intestinal gastric adenocarcinoma (2 papers, 2019 to 2025). "We obtained surgical biopsies from stage IIA intestinal gastric adenocarcinoma along with matched-normal epithelium from two patients and measure the protein expression of MLH1 and PMS2 to validate the presence of tumor cells." (PMID 31829268, 2019).
intraepithelial neoplasia (2 papers, 2020 to 2022). A precancerous neoplastic process that affects the squamous, glandular, or transitional cell epithelium without evidence of invasion.
lung adenocarcinoma (2 papers, 2022 to 2024). A carcinoma that arises from the lung and is characterized by the presence of malignant glandular epithelial cells. "We analyzed the genomic characteristics of 337 primary early-stage lung adenocarcinomas from patients in the TCGA M0 Stage LUAD cohort, revealing an absence of PMS2 alterations." (PMID 38714954, 2024).
Muir-Torre syndrome (2 papers, 2023 to 2025). Muir-Torre syndrome (MTS) is a form of hereditary nonpolyposis colon cancer (HNPCC) characterized by cutaneous sebaceous tumors, keratoacanthomas and at least one visceral malignancy, most frequently gastrointestinal carcinoma.
pancreatic adenocarcinoma (2 papers, 2021 to 2022).
pediatric cancer (2 papers, 2020).
primary immunodeficiencies (2 papers, 2018). "WES revealed heterogeneous genetic background among CVID patients with tumors, identifying gene variants associated with primary immunodeficiencies (such as CTLA4, PIK3CD, PMS2) and/or increased cancer susceptibility (including BRCA1, RABEP1, EP300, KDM5A)." (PMID 30723478, 2018).
renal carcinoma (2 papers, 2014 to 2019). A carcinoma arising from the epithelium of the renal parenchyma or the renal pelvis.
thyroid nodule (2 papers, 2024 to 2025). A small circumscribed mass in the THYROID GLAND that can be of neoplastic growth or non-neoplastic abnormality. "This case illustrates the rare convergence of PTEN and PMS2 germline mutations in a pediatric patient presenting with thyroid nodules." (PMID 41416262, 2025). "We report a case of a 15-year-old female with thyroid nodules whose evaluation revealed pathogenic variants in both PTEN and PMS2, and we explore the clinical implications of this overlap." (PMID 41416262, 2025). "We present a 15-year-old female with a thyroid nodule, ultimately found to harbor dual germline mutations in the PTEN and PMS2 genes." (PMID 41416262, 2025).
tubular adenoma (2 papers, 2016 to 2021). A usually polypoid neoplasm arising from the glandular epithelium. "The tubular adenoma with high-grade dysplasia was characterized by a BRAF p.V600E mutation and mismatch repair deficiency (loss of MLH1/PMS2)." (PMID 33712927, 2021).
adenosarcoma (1 paper, 2023). A low grade malignant neoplasm characterized by the presence of a benign epithelial component (tubular and cleft-like glands) and a low grade sarcomatous component that contains varying amounts of fibrous and smooth muscle tissues.
alcoholic liver diseases (1 paper, 2014). A disorder caused by damage to the liver parenchyma due to alcohol consumption.
anaplastic ependymoma (1 paper, 2022). Anaplastic ependymoma is a rare, malignant type of ependymoma that most often arises in the supratentorial region of the brain of children and young adults and that manifests with variable symptoms including headaches, nausea, vision impairment, memory loss and difficulty walking. "The pathogenic indel in PMS2 was identified in a patient with anaplastic ependymoma (P2955), confirmed on central pathology review." (PMID 35449451, 2022).
Autoimmunity (1 paper, 2018). The occurrence of an immune reaction against the organism's own cells or tissues. "We detected antinuclear antibodies in two of the five tested individuals in this cohort (P6, 26 years old and P11, 7 years old), both PMS2-deficient and asymptomatic with regards to autoimmunity." (PMID 30013564, 2018).
Azoospermia (1 paper, 2012). Absence of any measurable level of sperm,whereby spermatozoa cannot be observed even after centrifugation of the semen pellet. "One intronic SNP in MLH1 (rs4647269) and two non-synonymous SNPs in PMS2 (rs1059060, Ser775Asn) and MSH5 (rs2075789, Pro29Ser) seem to be risk factors for the development of azoospermia or oligozoospermia." (PMID 22594646, 2012).
benign prostatic hyperplasia (1 paper, 2015). A non-cancerous nodular enlargement of the prostate gland. "Additionally, PMS2 expression including both RNA and protein were found to be much lower in PCa when compared to benign prostatic hyperplasia (BPH) tissue; and a significant inverse correlation between Gleason score and PMS2 expression was observed in PCa, making it a good marker of progression." (PMID 26036629, 2015).